RHBDF2 (rhomboid 5 homolog 2)
Diseases named in the same sentence as RHBDF2 in open-access papers (continued):
Sharing a sentence is not in itself a finding about the gene and the disease.
cancer (18 papers, 2014 to 2026). A tumor composed of atypical neoplastic, often pleomorphic cells that invade other tissues. "Therefore, an inactive rhomboid protease known as iRhom2 encoded by the gene RHBDF2 can be considered an important target for cancer treatment." (PMID 36452073, 2022). "We found that, although high level of RHBDF2 correlated with increased infiltration of lymphocytes in cancer tissues, artificially overexpressed RHBDF2 led to an inhibition of the activity of the infiltrated immune cells through sustaining PD-L1 protein level." (PMID 34736454, 2021). "Advanced analyses of KIRC, like WGCNA, GO/KEGG pathways annotation pointed to the regulatory role of RHBDF2 in cell proliferation and migration, implicating its potential as a target for cancer therapy." (PMID 34736454, 2021). "Larger proportion of patients younger than 60-year-old or patients with advanced cancers had higher expression level of RHBDF2." (PMID 34736454, 2021). "First, the mRNA level of RHBDF2 was investigated in human cancers with the TIMER database, and we found that RHBDF2 mRNA expression was upregulated in most human tumors, including HCC (LIHC)." (PMID 36943228, 2023). "As shown in the pan-cancer view, the 4 hub genes (IFI16, LMNB1, RHBDF2, and TACC3) were significantly up-regulated in ccRCC samples and other cancer types when compared to adjacent normal tissues (p < 0.001)." (PMID 33796525, 2021). "Additionally, RHBDF2 overexpression activated TGF‐β signaling and enhanced the aggressiveness of cancer cells in gastric cancer." (PMID 36943228, 2023). "The result of immune infiltration analysis is interesting, high levels of RHBDF2 positively correlates with infiltration of lymphocytes in cancer tissues but is not conductive to the survival of patients." (PMID 34736454, 2021). "However, progression to carcinoma is not as simple, and we found no literature for studying mRNA expression of RHBDF2 during neoplastic growth, i.e., cancer initiation and progression." (PMID 36452073, 2022).
tumor (12 papers, 2017 to 2026). "High RHBDF2 expression was positively associated with tumor stage, tumor size and extent of tumor invasion." (PMID 36943228, 2023). "For the tumor stage, RHBDF2 overexpression was associated with unfavorable DSS in stage 1 HCC patients and related to bad OS and RFS in stage 3 HCC patients." (PMID 36943228, 2023). "For the tumor grade, RHBDF2 overexpression was linked ed to unfavorable OS in stage 1 HCC patients and poor RFS in grade 3 HCC patients, and was related to worse OS, PFS, RFS and DSS in stage 2 HCC patients." (PMID 36943228, 2023). "High expression of RHBDF2 in KIRC is associated with an activation of a number of genes involved in tumor growth and metastasis." (PMID 34736454, 2021). "To evaluate the association between RHBDF2 and the tumor microenvironment in HCC tissues, we investigated the link between RHBDF2 and immune checkpoint genes." (PMID 36943228, 2023). "Several recent studies have suggested that RHBDF2 is significantly upregulated in tumors and has pro‐tumor effects." (PMID 36943228, 2023). "The UALCAN database was utilized for further investigation of RHBDF2 expression in each tumor and corresponding normal tissues, which was consistent with the analysis of the TIMER database." (PMID 36943228, 2023). "According to the tumor stage, RHBDF2 overexpression in HCC patients in stages 1, 2, and 3 was observed compared to normal liver tissue." (PMID 36943228, 2023). "Based on tumor grade, significant overexpression of RHBDF2 was observed in HCC patients in grades 1, 2, and 3 compared to normal liver tissue." (PMID 36943228, 2023). "At the same time, we also observed a delay in the early stage of tumor formation in RHBDF2-knockdown group." (PMID 34736454, 2021). "The tumor growth rate in the RHBDF2-knockdown group was significantly slower than that in the control group." (PMID 34736454, 2021). "We performed immunohistochemical staining in the specimens of KIRC patients with different stages and tumor grades, and found that the RHBDF2 protein was substantially more abundant in high-grade tumors." (PMID 34736454, 2021). "Meanwhile, we detected the reduction of phospho-EGFR in RHBDF2 knockdown cells, and the phenomenon was also remarkable in the tumor sections of 786-O xenografts." (PMID 34736454, 2021). "c Statistics of RHBDF2 staining in tumor and adjacent tissues (n = 75, P-value was from the paired t-test)." (PMID 34736454, 2021). "Histological analysis revealed significantly increased tumor size and an increased number of polyps in ApcMin/+ Rhbdf2+/cub mice compared with ApcMin/+ Rhbdf2+/+ mice." (PMID 30022999, 2018). "Together, these data suggest that GOF mutations in RHBDF2 accelerate tumor growth with an associated increase in AREG secretion, suggesting a critical role for RHBDF2 in controlling tumor growth through enhanced secretion of AREG." (PMID 30022999, 2018). "Therefore, RHBDF2 has a multifaceted influence on the tumor immune microenvironment, which has a pro‐tumor effect." (PMID 36943228, 2023). "Furthermore, RHBDF2 can impact the prognosis of HCC patients partly because of tumor immune infiltration in HCC." (PMID 36943228, 2023). "Furthermore, our research implied that RHBDF2 upregulation was significantly linked to immune cell infiltration and revealed a potential molecular mechanism by which that RHBDF2 can impact the prognosis of HCC patients partly because of tumor immune infiltration." (PMID 36943228, 2023). "Meanwhile, RHBDF2 had an increased expression in tumor tissue, which was validated in datasets GSE47032, GSE68417, and GSE126964 and that high RHBDF2 levels were positively correlated with tumor grades." (PMID 34736454, 2021). "Additionally, a strong correlation between RHBDF2 upregulation and immune checkpoint genes (PDCD1, CD274, LAG3, CTLA4, TIGIT, HAVCR2) was observed in HCC, and these immune checkpoint genes can contribute to tumor immune escape and promote tumor progression." (PMID 36943228, 2023).
infection (5 papers, 2015 to 2023). The state of being infected such as from the introduction of a foreign agent such as serum, vaccine, antigenic substance or organism. "Our results also indicated the downregulation of certain proteins after infection with H37Ra such as inactive rhomboid protein 2 (RHBDF2), canopy-2 (CNPY2), hypoxia upregulated protein 1 (HYOU1), and protein transport protein sec23A (SC23A)." (PMID 25785198, 2015).
metabolic disease (3 papers, 2020 to 2024). A congenital disorder (due to inherited enzyme abnormality) or acquired (due to failure of a metabolically important organ) disorder resulting from an abnormal metabolic process. "The current findings suggest that Trim31 is an endogenous inhibitor of Rhbdf2 and downstream cascades in the pathogenic process of steatohepatitis and that it may serve as a feasible therapeutical target for the treatment of NAFLD/NASH and associated metabolic disorders." (PMID 35217669, 2022).
neurodegenerative disease (1 paper, 2024). A disorder of the central nervous system characterized by gradual and progressive loss of neural tissue and neurologic function. "Our comparative analysis of RHBDF2 and TNFRSF10B expression in various neurodegenerative diseases has revealed that their heightened expression is distinctive to AD, contrasting conditions like PD, FTD, DLB, and HD." (PMID 38915415, 2024). "Expression characteristics of RHBDF2 and TNFRSF10B in multiple neurodegenerative diseases." (PMID 38915415, 2024).
RHBDF2 also shares sentences with these, for which no sentence is quoted: viral infection (6 papers); colitis (4); hepatocellular carcinoma (4); Hyperkeratosis (4); myocardial infarction (4); Obesity (4); rheumatoid arthritis (4); genetic disorder (3); lupus nephritis (3); non-alcoholic fatty liver disease (3); Arthritis (2); bacterial infection (2); diabetes (2); diabetic kidney disease (2); inflammatory bowel disease (2); nonalcoholic steatohepatitis (2); oral squamous cell carcinomas (2); Sepsis (2); acute lung injury (1); acute myocardial infarction (1); Alcohol (1); arthropathy (1); Ataxia (1); Autoimmunity (1); bacterial sepsis (1); Barrett's oesophagus (1); bile duct obstruction (1); colorectal cancer (1); colorectal tumour (1); Crohn disease (1).
A further 28 diseases each share a sentence with RHBDF2 in 1 paper.